GBP1 (guanylate binding protein 1)
Diseases named in the same sentence as GBP1 in open-access papers (continued):
Sharing a sentence is not in itself a finding about the gene and the disease.
infection (continued). "Expression of Gbp5 was strongly induced upon infection with T. gondii, while Gbp2 and Gbp7 were induced at lower levels, and no substantial change was seen in Gbp1 or Irga6." (PMID 30154263, 2018). "Similar to infection with S. flexneri, expression of WT, but not catalytically inactive IpaH9.8, drastically reduced levels of GBP1, GBP2, and GBP4, but not GBP3." (PMID 29024643, 2017). "Similarly, expression of GBP1, NLRP3, and IL1B was downregulated in both HIF1‐KD and GBP1‐KD macrophages, while expression of ASC1 and HIF1A was upregulated in HIF1‐KD and GBP1‐KD macrophages, respectively, upon H37Rv infection, compared with controls." (PMID 41287823, 2025). "Together, these data indicate that both HIF1α and GBP1 are involved in inflammasome activation in THP‐1 macrophages upon infection, although it may be independent of the nature of the infecting Mtb strain." (PMID 41287823, 2025). "A recent study further revealed that type I IFN signaling drives Caspase-11-dependent activation of the non-canonical NLRP3 inflammasome, while the IFN-inducible protein GBP1 enhanced host resistance to infection by promoting inflammasome activation rather than through direct bacterial killing." (PMID 40525851, 2025). "Our analysis did not detect the presence of GBP1, implying that GBP1 might be recruited during earlier stages of infection." (PMID 38565565, 2024). "Infection with HCV resulted in a perinuclear accumulation of GBP1, which could not be observed in the GND control cells, where GBP1 is equally distributed in the cytoplasm." (PMID 38315728, 2024). "Although induction of GBP1 expression is not an essential component for caspase‐4 activation, for example during infection with EPEC, future work should also investigate whether GBP1 or other GBPs can overcome the reduced inflammasome activation by very long LPS O‐antigen chains." (PMID 33355403, 2021). "In a previous in vitro study based on the infection of human endothelial cells with R. conorii, we have identified increased expression of GBP1 independent of IFN-β expression, and the activation of inflammasome by the host as an anti-rickettsial strategy has also been demonstrated." (PMID 30857242, 2019). "We found that the role of GBP1 in cell death could be bypassed by transfecting molecules from Tg or STm, but not during natural infection, pointing to its role in liberating microbial ligands." (PMID 31268602, 2019). "It is conceivable that global Gbp1 and Gbp2 ubiquitination status might not change during infection, while this modification might target the defence proteins specifically to Toxoplasma PVs to excert their function." (PMID 29510761, 2018). "Similarly, ISGs (IFIT1–2, GBP1, OASL) have been detected in MDMs 6 h post in vitro infection with ZEBOV-Mayinga (EBOV strain isolated in 1976) in the absence of increased IFNα/β expression." (PMID 29123522, 2017). "In addition, studies have shown that expression of GBP1-3, GBP5, and GBP7 in mice is significantly upregulated 4 h after infection with B. abortus, with GBP5 expression beginning to rise as early as 2 h post-infection and remaining the highest among all GBPs at each time point." (PMID 40606156, 2025). "We report a novel mechanism of inflammasome activation mediated by GBP1 and HIF‐1α, which orchestrates differential inflammasome activation and inflammatory response in macrophages and in vivo upon infection with Mtb strains that cause a progressive or nonprogressive infection." (PMID 41287823, 2025). "GBP1‐knockout THP‐1 (ΔGBP1) cells created with CRISPR/Cas9 (Fig EV1D), also failed to undergo cell death upon Tg infection and provided an independent verification of siRNA experiments." (PMID 31268602, 2019).
infection (continued). "As expected, expression of GBP-1 was vastly reduced in H5N1 infected JH4 cells overexpressing RIG-I and MAVS with concurrent GBP-1 knockdown at both 12 and 24 hours post infection relative to cells overexpressing RIG-I and MAVS without GBP-1 knockdown." (PMID 28418930, 2017). "We have used complementary approaches to demonstrate that neither overexpressed or endogenous mouse guanylate‐binding protein (GBP) 1, an intracellular GTPase, plays a major role in modulating influenza A virus (IAV) infection in vitro nor did it modulate IAV in a mouse model of infection." (PMID 36744765, 2023).
tumor (76 papers, 2008 to 2026). "In the tumor immunocorrelation analysis of GBP1, we found that GBP1 was significantly associated with a large number of immunoinfiltrating cells." (PMID 38167153, 2024). "GBP1, encoding Guanylate Binding Protein 1, is related to tumor progression and chemotherapy drug resistance." (PMID 37090691, 2023). "Positive correlations were also observed between GBP1 expression and the expression of immune checkpoints, as well as tumor mutation burden (TMB)." (PMID 35222540, 2022). "Correlation analysis of clinical parameters of LGG patients indicated that the expressions of GBP 1, 2, 3, 4 were significantly associated with the histological subtype and tumor histological grade of LGG." (PMID 34759950, 2021). "This pro-tumor role involves GBP1’s association with EGFRvIII, a constitutively active mutant, driving actin cytoskeleton remodeling and extracellular matrix degradation to facilitate tumor spread." (PMID 40564939, 2025). "GBP1 protein overexpression is associated with radioresistance in multiple cancers and is mainly regulated at the transcriptional step, and GBP1 knockdown by siRNA suppressed radioresistance in vitro and in xenotransplanted tumor tissues." (PMID 40564939, 2025). "In addition, upregulated GBP-1 mRNA was correlated/associated with EGFRvIII expression in 20 GBM tumor samples." (PMID 39457021, 2024). "In addition, GBP1 expression was strongly associated with elevated immune cell infiltration, expression of immune checkpoints, activated anti-tumor immunity, and improved overall survival (OS) for patients treated with immunotherapy." (PMID 35222540, 2022). "Also, GBP1 mutation facilitated the intratumoral immune cell infiltration, resulting in elevated anti-tumor responses and a better prognosis of UCEC patients." (PMID 35222540, 2022). "To further explore the clinical significance of GBPs, we analyzed the correlation between their expressions and the clinical parameters of LGG patients, and we found that the expressions of GBP 1, 2, 3, and 4 were significantly associated with tumor histological grade of LGG." (PMID 34759950, 2021). "Seven guanylate-binding proteins (GBPs, GBP1–7), identified as a subfamily of interferon-γ-induced guanosine triphosphate hydrolases (GTPases), has been reported to be closely associated with tumor progression, metastasis, and prognosis of cancer patients in recent years." (PMID 34759950, 2021). "GBP1 encodes ornithine-binding protein, and plays an important role in both immunity and tumor." (PMID 33194692, 2020). "It is tempting to speculate that the correlation of high GBP1 mRNA expression and better survival, could reflect an underlying anti-tumor T cell response." (PMID 32093058, 2020). "In univariate analysis, we found that tumor stage (HR = 1.80, 95% CI: 1.23–2.66, P < 0.05), T-stage (HR = 1.36, 95% CI: 1.05–1.76, P < 0.05), N-stage (HR = 1.36, 95% CI: 1.10–1.68, P < 0.05), high expressions of GBP1/6/7 were linked to shorter OS of HNSCC patients." (PMID 32269280, 2020). "Therefore, besides the possible anti-tumor effects of GBP1, the presence of soluble GBP1 could represent a potential marker of an underlying Th1 response in the tumor environment." (PMID 32093058, 2020). "For instance, indicators associated with the IFN pathway, such as the characteristics of interferon-stimulated genes (ISGs) including MX1, EPSTI1, XAF1, and GBP1, have been correlated with tumor sensitivity to VSV." (PMID 40698086, 2025). "GBP-1 displays relatively strong expression in infiltrating cells while exhibiting weak expression in tumor cells, which elucidates the spatial interaction pattern between HLA-B and GBP-1." (PMID 39954675, 2025). "Consistently, in vivo xenograft experiments demonstrated that GBP1 depletion suppressed tumor growth, while GBP1 re-expression rescued tumorigenic potential." (PMID 40975978, 2025).
tumor (continued). "GBP1 was also found to facilitate immune evasion by promoting extracellular secretion of indoleamine 2,3-dioxygenase, thereby enhancing tumor malignancy." (PMID 41009979, 2025). "Genes such as HLA-B, TGM2 and GBP1 tend to exhibit high connectivity degrees across most tumor and normal regions." (PMID 39954675, 2025). "Unlike with normal EGFR, U87-EGFRvIII promoted cell proliferation and KD of GBP-1 in U87-EGFRvIII cells significantly inhibited tumor growth in vitro." (PMID 39457021, 2024). "This study comprehensively analyzed the role and potential function of GBP1 in anti-tumor immunity and immunotherapy." (PMID 38758367, 2024). "We also described the specific upregulation of GBP1 in the tumor cells as consequence of T cell interactions." (PMID 39262976, 2024). "EGFRvIII overexpression in U87 cells promoted tumor growth in subcutaneously inoculated mice compared to parental cells, and the KD of GBP-1 in these cells significantly inhibited tumor growth." (PMID 39457021, 2024). "Elevated expression of GBP-1 promoted cell invasion in xenograft intracranial injections and resulted in much larger tumor volumes." (PMID 39457021, 2024). "For example, GBP1 increases the tolerance of tumor cells to some drugs and has a strong correlation with the PD-1/PD-L1 pathway." (PMID 38167153, 2024). "Further analysis showed that GBP1 mRNA and protein expression in baseline tumor tissues correlated with improved response and overall survival (OS) in multiple cohorts." (PMID 38758367, 2024). "Intracellular expression of GBP-1 inhibits angiogenesis in endothelial cells, and inhibits proliferation and migration in tumor cells and intestinal epithelial cells, while preventing cell apoptosis." (PMID 37645250, 2023). "In the third step, the GBP1/hsa-miR-30d-5p/GBP1P1 axis expression level was assessed in 40 tumor/normal BC patients and MCF-7 cell lines." (PMID 38072995, 2023). "We compared the correlation of BC patient clinical information (age, menopause status, metastasis, tumor stage, and tumor subclass) to GBP1 and PDE4DIP expression." (PMID 38072995, 2023). "Clustering analysis explored the relationship between GBP1 expression and anti-tumor immune phenotypes." (PMID 35222540, 2022). "Our next work will investigate if it is feasible to alter the tumor immune microenvironment by targeting GBP1." (PMID 35222540, 2022). "Tumors with higher GBP1 expression had significantly lower tumor purity, more stromal cells, and infiltrating immune cells." (PMID 35222540, 2022). "Previous studies found the crucial role of GBP1 in tumor proliferation, metastasis, and treatment resistance." (PMID 35222540, 2022). "This study lacks investigation of the mechanism of GBP1 in acting directly within cancer cells or tumor microenvironment." (PMID 35222540, 2022). "By analyzing the mRNA expression of GBPs in pan-cancer, we found that GBP1-5 were highly expressed in tumor tissues, while GBP6 and GBP7 were less expressed." (PMID 36246628, 2022). "GBP1 was expressed most robustly in the infiltrating cells but also in the tumor cells of the recurrence-free group." (PMID 35681772, 2022). "What is becoming increasingly clear is that GBP-1′s activity is dependent on tumor type and tumor environment." (PMID 35681772, 2022). "It is increasingly clear that GBP-1 cannot be used as a single marker for tumor prognosis but needs to be considered within the tumor type and growth factor environment." (PMID 35681772, 2022). "Evaluated by multiple algorithms, tumors with higher GBP1 expression had more infiltration by immune and stromal cells and lower tumor purity." (PMID 35222540, 2022). "In conclusion, our pan-cancer analysis of GBP1 indicated positive correlations between GBP1 and intratumoral immune infiltration, activation of immune-related pathways, and anti-tumor immune response in multiple cancer types." (PMID 35222540, 2022).
tumor (continued). "A number of interferon-stimulated genes (ISGs) were found to be highly induced in tumor compared to non-tumor samples, such as GBP1, CAMP, PTGS2, GOLIM4, IFIT3, MX1, LTF, and CYBB." (PMID 34400640, 2021). "As the tumor histological grade increased, the expressions of GBP 1, 2, 3, and 4 significantly increased." (PMID 34759950, 2021). "The correlation between the expression of GBP 1, 2, 3, 4 and the expressions of other immune cell marker genes were assessed, further confirming the close connection between GBP 1, 2, 3, 4 and tumor immune-infiltrating cells." (PMID 34759950, 2021). "The cox proportional hazard model of GBP1/2/3/4 and six tumor-infiltrating immune cells in KIRC (TIMER)." (PMID 34759950, 2021). "Our results indicated that GBP1, 2, 3, 4 were potential biomarkers that can be used to predict prognosis and tumor immune infiltration of LGG patients." (PMID 34759950, 2021). "The results showed that after IDO1 and GBP1 were knocked down, tumor volumes were decreased, and the tumor volume was the smallest in the IDO1 and GBP1 group." (PMID 33552086, 2020). "Further studies to identify the mechanistic role of soluble GBP1 in the tumor environment of EOC and/or its role as a biomarker of an underlying immune response are warranted." (PMID 32093058, 2020). "When the diameter of the tumor reaches 5 mm, GBP1 and IDO1 knock-down lentivirus were used for intertumoral injection." (PMID 33552086, 2020). "Further multivariate analysis revealed that GBP1 expression (p < 0.001) and the residual tumor margins (p=0.003) were independent predictors for overall survival in HGSOC patients." (PMID 32544083, 2020). "Another four genes, GBP1, GBP5, LY6E and OAS2, have also been reported to be associated with a variety of other tumor progression." (PMID 33223511, 2020). "A paired analysis performed on ascites and sera from the same patients showed that GBP1 preferentially accumulates at higher levels in the ascites, further supporting local GBP1 release at the tumor site." (PMID 32093058, 2020). "And astragaloside IV can assist the anti-tumor effect of PD-1 by blocking the binding of GBP1 and IDO1." (PMID 33552086, 2020). "Univariate analysis of overall survival revealed that GBP1 levels (p < 0.001), the residual tumor margins (p=0.003), diaphragmatic metastasis (p = 0.013) and mesenteric metastasis (p=0.021) were prognostic indicators in HGSOC." (PMID 32544083, 2020). "Observation of CD3+CD8+ T lymphocyte and HLA‐DRA+CD163+ macrophage infiltration in these tumors, and demonstration of GBP1 expression in tumor cells also attested to the activation of this pathway." (PMID 31025552, 2019). "Comparatively, GBP1 KO xenograft tumor volume over time in both groups was significantly smaller than that in the corresponding control group (p < 0.001 for the DU145, and p < 0.001 for the PC3 cells)." (PMID 31998647, 2019). "This is due to a direct interaction of T cells with tumor cells, leading to increased guanylate binding protein 1 (GBP)-1 expression by the latter, which in turn enables them to cross the BBB." (PMID 31396225, 2019). "The xenograft experiments verified a significantly slower tumor growth of the GBP1 KO cells in nude mouse model." (PMID 31998647, 2019). "Xenograft experiments verified a significantly slower tumor growth of the GBP1 KO cells in nude mouse model." (PMID 31998647, 2019). "GBP1 protein was detected mainly in tumor cell membrane and cytoplasm, but also in some immune cells." (PMID 31025552, 2019). "Co-culturing of ErbB2 tumor cells with activated T cells induced a significant increase in Gbp1 expression by the cancer cells." (PMID 29350274, 2018). "The prominent effect of GBP1 on the capacity of tumor cells to cross the modelled BBB was examined by silencing experiments." (PMID 29350274, 2018). "GBP1 positive cells were detected in tumor areas, where T lymphocytes invaded from the stroma in between the tumor cells." (PMID 29350274, 2018).